INS (insulin)
Diseases named in the same sentence as INS in open-access papers (continued):
Sharing a sentence is not in itself a finding about the gene and the disease.
Insulin resistance (continued). "Circulating insulin is dependent on hepatic extraction and hepatic insulin resistance, and therefore fasting connecting peptide (C-peptide), a marker of insulin secretion, is important to analyze in T2D." (PMID 39273678, 2024). "This disruption in insulin signalling promotes hyperglycaemia and compensatory hyperinsulinemia, ultimately contributing to the development of insulin resistance." (PMID 38391792, 2024). "In a state of insulin resistance, while insulin signaling is impaired, insulin levels remain elevated; this hyperinsulinemia can promote the production and release of inflammatory factors." (PMID 39459158, 2024). "A clinical benchmark defines a patient as insulin-resistant if more than 1 unit/kg/day of exogenously administrated insulin is required and daily needs exceeding 200 units per day are considered severe insulin resistance." (PMID 39768947, 2024). "The findings from IP-ITT demonstrated that T2DM mice exhibited classic insulin resistance, whereas the exercise intervention partially improved insulin sensitivity in T2DM mice." (PMID 38540669, 2024). "Significant differences were observed among these groups in body weight; BMI; WC; systolic blood pressure; and albumin, FBG, HbA1c, TG, HDL-C, AST, ALT, insulin, insulin resistance, and hs-CRP levels." (PMID 39408311, 2024). "Insulin resistance occurs when cells experience diminished sensitivity to insulin, resulting in prolonged episodes of hyperglycemia." (PMID 39596529, 2024). "Capivasertib has the potential to induce severe insulin resistance, requiring aggressive insulin management." (PMID 39099917, 2024). "Insulin resistance is characterised by decreased insulin‐mediated glucose utilisation, resulting in decreased sensitivity and responsiveness to insulin, and the inability to maintain a steady state of blood glucose." (PMID 39083321, 2024). "Data collection involved medical history, anthropometric measurements, blood pressure, and biochemical assessments including FBS, HbA1c, lipid profiles, insulin levels, and insulin resistance." (PMID 39479098, 2024). "Pathophysiologically, T2DM is characterized by insulin resistance and impaired insulin signaling pathways, leading to an inadequate cellular response to insulin." (PMID 39000103, 2024). "The present study implied that EPE diminished visceral obesity and hyperlipidemia and improves insulin resistance by lowering mTOR/S6K1 signaling proteins but elevating insulin sensitivity both in peripheral tissues." (PMID 39329975, 2024). "The TyG index, a simple surrogate marker of insulin resistance, has been shown to have a similar ability to evaluate insulin sensitivity as the hyperinsulinemic–euglycemic clamp." (PMID 39136595, 2024). "From these results, we conclude that sulpiride acts as a normoglycemic agent in obesity via the systemic increase in insulin sensitivity, the prevention of hyperinsulinemia, and the reduction of insulin resistance." (PMID 38635745, 2024). "Obesity and excess free fatty acids not only lead to muscle insulin resistance but also induce hepatic insulin resistance and reduce insulin clearance." (PMID 39408924, 2024). "Activated JNK acts on nuclear factor-κb (NF-κB) and activator protein-1 (AP-1) to produce more inflammatory factors, further reduce the sensitivity of insulin target cells to insulin, and eventually form a vicious cycle and aggravate insulin resistance." (PMID 38436035, 2024). "Similar to humans, several studies have reported that obesity in cats leads to peripheral insulin resistance and increased insulin concentrations." (PMID 39328456, 2024). "The mixture of these inflammatory factors also disrupts the normal insulin-associated PI3-K/AKT pathway, causing insulin resistance." (PMID 38917217, 2024). "Hyperinsulinemia, a compensatory response to peripheral insulin resistance, can lead to reduced insulin transport across the blood–brain barrier, resulting in decreased insulin availability in the brain." (PMID 39659426, 2024).
Insulin resistance (continued). "In adipocytes, mitochondrial dysfunction-induced oxidative stress can also lead to disturbed insulin signaling in the cell and, consequently, insulin resistance." (PMID 38892574, 2024). "Insulin resistance, also known as impaired insulin sensitivity, occurs when cells in the muscles, fat, or liver do not respond adequately to insulin." (PMID 38195616, 2024). "The studies of mechanisms showed JLD can ameliorate insulin resistance by up-regulating the insulin signaling pathway and reducing skeletal muscle lipid content." (PMID 38704482, 2024). "Insulin sensitivity in HFD‐fed mice is often tested with higher insulin amounts due to developing insulin resistance; however, the higher levels of insulin induced hypoglycemia and it was not possible to complete the test for proper conclusions." (PMID 39054559, 2024). "However, we aimed to investigate whether other markers of glucose homeostasis in addition to hyperglycaemia (i.e. insulin resistance and insulin sensitivity) are associated with early metabolic retinal alterations prior to the development of diabetic retinopathy." (PMID 38431705, 2024). "Resistin is a proinflammatory adipokine secreted from adipose tissue, and in mice, it has been connected to insulin sensitivity and insulin resistance." (PMID 38999854, 2024). "Aggravated insulin resistance was further confirmed by remarkable suppression of Akt phosphorylation in the liver, eWAT and skeletal muscle in B3galt5−/− mice after insulin administration." (PMID 39004626, 2024). "One trial had a four-armed design comparing adjunctive pioglitazone versus adjunctive placebo in the insulin resistance or insulin sensitive group." (PMID 38398483, 2024). "Rats fed a high sucrose diet for an extended period developed hyperglycemia and insulin resistance, while mice fed high sucrose diet developed glucose intolerance and impaired insulin secretion." (PMID 38414818, 2024). "Insulin resistance is defined as an impaired response of these targets to insulin stimulation, which leads to hyperglycemia due to decreased glucose utilization and hyperinsulinemia due to compensatory insulin production." (PMID 38612468, 2024). "Type 2 diabetes is a metabolic disease in which the driving force for insulin resistance and impaired insulin secretion lies in patient’s overweight or obesity." (PMID 39839113, 2024). "Secondary outcomes included body weight (BW), waist circumference (WC), insulin levels, glycated haemoglobin (HbA1c), homeostatic model assessment of insulin resistance (HOMA-IR), aspartate aminotransferase (AST), and alanine aminotransferase (ALT)." (PMID 38999920, 2024). "M1 macrophages do not require insulin for glucose uptake, and the release of ROS and IL-1β contributes to insulin resistance in insulin target cells, including adipocytes, hepatocytes, and myocytes." (PMID 39063184, 2024). "Allocholic acid, a potent of insulin secretion stimulator, exhibits varying effects on insulin resistance." (PMID 38254447, 2024). "The present study suggests that VGX and AO synergistically impaired insulin secretion and increased insulin resistance." (PMID 39063072, 2024). "Elevated hemoglobin can increase blood viscosity, which can potentially decrease the supply of oxygen, glucose, and insulin to vital tissues, ultimately leading to insulin resistance." (PMID 38840960, 2024). "PI3K signaling plays an important role in insulin signaling and glucose homeostasis, and the inhibition of this pathway leads to insulin resistance (manifested as hyperglycemia) and is due to the feedback activation of insulin signaling." (PMID 38542151, 2024). "Conversely, insulin resistance refers to a condition where cells exhibit reduced responsiveness to insulin, resulting in elevated levels of glucose in the bloodstream." (PMID 38711066, 2024).
Insulin resistance (continued). "First, we noted that, in aged HFD-fed Foz mice, insulin resistance was alleviated as high insulin production successfully controlled blood glucose homeostasis in aged HFD-fed Foz unlike in younger ones, as shown here in the fasting state." (PMID 39206703, 2024). "This study suggests that T2DM patients with low education level, history of insulin application, high insulin resistance, low serum IGFBP-3, and low creatinine values are more susceptible to MCI." (PMID 38698772, 2024). "Chronic hyperglycemia and insulin resistance can lead to β-cell exhaustion and apoptosis, resulting in reduced insulin secretion over time." (PMID 38741878, 2024). "Insulin resistance (IR) is defined as a state in which insulin exhibits reduced responsiveness in target tissues, despite its sufficient secretion." (PMID 38572476, 2024). "Blood glucose levels and serum insulin levels of rats were evaluated to determine obesity-related insulin resistance." (PMID 39055496, 2024). "Many of the effects of adiponectin appear to be paradoxicales with adiponectin, such as its proven ability to increase systemic insulin sensitivity, however, insulin resistance can also occur at high adiponectin levels." (PMID 38813109, 2024). "For example, M1-EVs contribute to obesity-induced insulin resistance by activating the NF-κB signaling pathway, reducing insulin signaling, and decreasing glucose uptake in human adipocytes." (PMID 39896803, 2024). "In type 2 diabetes, insulin resistance is characterized by inflammation and altered autophagy in all insulin-targeted tissues, and these factors are closely interconnected with mitochondrial dysfunction and metabolic cellular stress." (PMID 39519269, 2024). "The main characteristic of insulin resistance is interference with insulin signaling, which results in insulin resistance." (PMID 39640295, 2024). "By investigating the impact of CXCR1/2 inhibition on TNF-α induced insulin resistance, this study seeks to provide insights into the potential therapeutic targeting of chemokine receptors to improve insulin sensitivity." (PMID 39627194, 2024). "Aging, a common risk factor for both AD neuropathology and the decline in brain insulin levels, contributes to the development of insulin resistance." (PMID 39769243, 2024). "OFS treatment in db/db mice dose-dependently prevented hyperinsulinemia, hyperglycemia, and glucose tolerance, including insulin resistance and quantitative insulin sensitivity check index." (PMID 39065815, 2024). "This sustained inflammation within adipose tissue and other target organs further disrupts insulin signaling pathways, thereby exacerbating insulin resistance." (PMID 39749015, 2024). "Insulin resistance impairs glucose disposal in skeletal muscle due to disrupted insulin signalling, glucose transport and glycogen synthesis, resulting in elevated blood glucose levels." (PMID 39339405, 2024). "The accumulation of sphingolipid derivatives, such as ceramides, induces cellular toxicity and insulin signaling defects, resulting in insulin resistance." (PMID 39519852, 2024). "Mainly, a dysfunctional central insulin signaling due to peripheral insulin resistance, immune-inflammatory pathways, and the hyperactivation of the HPA axis are considered key interconnected neurobiological mechanisms." (PMID 38218741, 2024). "In conclusion, our findings indicate that insulin induces insulin resistance in human DPSCs, resulting in impairments in proximal insulin signaling events (INSR, IGF1R, IRS1, and PI3K) while maintaining the activity of distal pathway components (AKT and mTOR)." (PMID 39075596, 2024). "The impact of diet and obesity on fertility is also connected with insulin resistance, occurring when insulin in the bloodstream is unable to effectively promote glucose uptake or utilization by insulin-sensitive organs and tissues." (PMID 39683543, 2024).
Insulin resistance (continued). "The postprandial measures of insulin resistance or glucose represent overall or peripheral insulin resistance because they give a combined picture of insulin response to oral glucose intake with uptake by skeletal muscle and fat tied to liver function." (PMID 39347227, 2024). "ROS can inhibit IRS1 activation, thereby impairing insulin signaling and aggravating insulin resistance." (PMID 39728000, 2024). "SHORT syndrome features short stature and insulin resistance consistent with impaired ligand-induced p110α action, a phenotype distinct from the enhanced insulin sensitivity produced by genetic ablation of one or more Pik3r1 products in mice." (PMID 38077044, 2024). "These macrophages are classified as (M1) pro-inflammatory macrophages, exacerbating insulin resistance, and (M2) anti-inflammatory macrophages, enhancing insulin sensitivity." (PMID 38826152, 2024). "In the early stages of obesity, β cells compensate for insulin resistance by expanding β-cell mass and increasing insulin secretion; this process can induce β-cell stress, ultimately resulting in β-cell failure and the onset of T2D." (PMID 38794702, 2024). "Experimental studies have demonstrated that SELENOP affects the phosphorylation of key molecules in the insulin signaling pathway, thereby impairing insulin signaling and leading to insulin resistance in hepatocytes and myocytes." (PMID 39149550, 2024). "The study also compared data such as serum insulin and control of comorbidities, establishing a direct relationship between weight loss, MMP-9,and improvement in insulin resistance and control of metabolic diseases in previously obese patients." (PMID 39766340, 2024). "This insulin resistance, compounded by obesity-induced inflammation, can disrupt insulin signaling, ultimately leading to glucose intolerance and metabolic disorders." (PMID 38816357, 2024). "Understanding which molecular mechanisms link IMCL to changes in insulin signaling is vital for the development of new therapies for treating insulin resistance." (PMID 39769002, 2024). "The ten different pathways to which these genes were grouped included the adipokine signaling pathway, regulation of lipolysis in adipocytes, nonalcoholic fatty liver diseases (NAFLD), insulin resistance, insulin signaling pathway, and T2DM." (PMID 38704700, 2024). "Inflammation, which activates catabolic pathways and suppresses anabolic pathways like insulin signaling, can lead to insulin resistance." (PMID 38420099, 2024). "Insulin resistance weakens the glucose-lowering effect of insulin in the body, leading to compensatory hyperinsulinemia." (PMID 38554189, 2024). "UA-induced insulin resistance models are especially useful for studying the effects of hyperuricemia on insulin signaling, lipid metabolism, and inflammation in hepatic cells." (PMID 39749015, 2024). "Skeletal muscle insulin resistance contributes to the development of type-2 diabetes while improvements in skeletal muscle insulin signaling are among key adaptations to exercise training." (PMID 38845596, 2024). "Type 2 Diabetes (T2D) is a condition that is often associated with obesity and defined by reduced sensitivity of PI3K signaling to insulin (insulin resistance), hyperinsulinemia and hyperglycemia." (PMID 38978604, 2024). "HOMA-IR values are widely used as indices of insulin resistance; however, their reliability decreases when the insulin secretion is reduced and hyperglycemia occurs." (PMID 38905235, 2024). "Studies have demonstrated that MEHHs’ phenolic acids, including CA, CGA, and SalB, enhance insulin sensitivity, modulate insulin signaling, and ameliorate insulin resistance." (PMID 39459158, 2024). "Our results revealed that ginseng extract effectively promoted pancreatic β-cell regeneration, improved the function of the pancreas, enhanced insulin secretion, alleviated insulin resistance, and decreased blood glucose levels." (PMID 38989151, 2024).
Insulin resistance (continued). "This obesity particularly abdominal obesity impedes insulin action and results in insulin resistance." (PMID 39639395, 2024). "Of the three known Akt isoforms (Akt1, Akt2, and Akt3) in insulin-sensitive tissues, defects in Akt2 and Akt3 particularly impair insulin-stimulated glucose transport in insulin resistance." (PMID 39125938, 2024). "A recent and timely study using gold standard tests (insulin infusion and graded glucose infusion tests) showed an increase in insulin resistance (but also an increase in insulin secretion) in those exposed to atorvastatin." (PMID 38376536, 2024). "Conversely, obese patients with severe hyperglycemia and insulin resistance had significant recovery with insulin therapy, along with a 40% rise in UDPGlcNAc concentrations in their muscles." (PMID 39061964, 2024). "The influence of diet and physical activity composition on insulin sensitivity in obese individuals is a prominent topic in the scholarly literature on RCTs focused on insulin resistance." (PMID 38195616, 2024). "In mice, the excessive consumption of 1200 or 2400 μg/L of iodide alters insulin, blood glucose levels, and the homeostasis model assessment for insulin resistance (HOMA-IR) index after 6 months." (PMID 39056661, 2024). "On the other hand, the liver shows only partial insulin resistance, since hepatic lipogenesis remains insulin-sensitive even in states of severe insulin resistance; thus, FFA influx to the liver is further increased." (PMID 37938366, 2024). "In terms of pathogenesis, impaired insulin secretion is the key operating mechanism, alongside with ectopic adiposity-related insulin resistance." (PMID 38472622, 2024). "This strategy can improve glucose metabolism in patients with diabetes and insulin resistance by reducing postprandial glucose levels and increasing peripheral insulin sensitivity." (PMID 39596891, 2024). "Systemic inflammation promotes desensitization to insulin and the establishment of insulin resistance, which is defined as a defect in insulin signaling and impaired systemic glucose uptake in adipose tissue, liver, and skeletal muscle." (PMID 39458933, 2024). "A key factor in the pathogenesis of GDM is insulin resistance, which is exacerbated during pregnancy due to hormonal changes, leading to inadequate insulin compensation and hyperglycemia." (PMID 38654206, 2024). "The most significant limitation of this study is the lack of a detailed molecular mechanism explaining how 1,2-diCA-PC enhances mitochondrial biogenesis, improves insulin response, and reverses insulin resistance." (PMID 39339765, 2024). "This study found that in women of childbearing age, the higher the methylation rate of the TGF-β1 gene, the lower the fasting insulin level and insulin resistance index, which also reflected the effect of the methylation rate on the IR phenotype." (PMID 38166771, 2024). "The main subtype is type 2 diabetes, which is characterized by insulin resistance and impaired insulin secretion." (PMID 38297165, 2024). "Insulin resistance (IR), a disorder characterized by reduced biological activity of insulin, leads to increased insulin secretion." (PMID 39631832, 2024). "Insulin resistance (IR), where more insulin than usual is needed to maintain normal blood glucose levels, often precedes T2D and significantly affects glucose regulation." (PMID 39531415, 2024). "All children underwent 2 h OGTT with measurements of glucose and insulin every 0.5 h, lipid profile, and other tests; indices if insulin resistance (IR): HOMA, QUICKI, Matsuda index, AUC (glu/ins) were calculated." (PMID 39125447, 2024). "It is an inhibitory cytokine that can attenuate the apoptosis of β-cells, suppression of insulin secretion, and peripheral insulin resistance induced by pro-inflammatory cytokines such as IL-6 and TNF-α." (PMID 39574905, 2024).